RORB (RAR related orphan receptor B)
Description:
Nuclear receptor that binds DNA as a monomer to ROR response elements (RORE) containing a single core motif half-site 5'-AGGTCA-3' preceded by a short A-T-rich sequence. Considered to have intrinsic transcriptional activity, have some natural ligands such as all-trans retinoic acid (ATRA) and other retinoids which act as inverse agonists repressing the transcriptional activity. Required for normal postnatal development of rod and cone photoreceptor cells. Modulates rod photoreceptors differentiation at least by inducing the transcription factor NRL-mediated pathway. In cone photoreceptor cells, regulates transcription of OPN1SW. Involved in the regulation of the period length and stability of the circadian rhythm. May control cytoarchitectural patterning of neocortical neurons during development. May act in a dose-dependent manner to regulate barrel formation upon innervation of layer IV neurons by thalamocortical axons. May play a role in the suppression of osteoblastic differentiation through the inhibition of RUNX2 transcriptional activity (By similarity). Isoform 1 is critical for hindlimb motor control and for the differentiation of amacrine and horizontal cells in the retina. Regulates the expression of PTF1A synergistically with FOXN4 (By similarity).
Synonyms: NR1F2; RZRB; ROR-BETA; RORβ; RZR-BETA; EIG15; RORbeta; bA133M9.1
Tractability: Small molecule: a high-quality ligand is known; it belongs to a druggable protein family. PROTAC: ubiquitination databases record sites on it; a small molecule that binds it is known.
Target class: Nuclear receptor; Nuclear hormone receptor subfamily 1; Nuclear hormone receptor subfamily 1 group F; Transcription factor
Gene: Protein-coding gene on chromosome 9 (74,497,335 to 74,693,177, forward strand). Ensembl gene ENSG00000198963.
Subcellular location: Nucleus, nucleoplasm
Subcellular location (Human Protein Atlas): Nucleoplasm
Pathways (Reactome):
Circadian clock: Expression of BMAL (ARNTL), CLOCK, and NPAS2
Gene expression (Transcription): Nuclear Receptor transcription pathway
Gene Ontology:
Molecular function: protein binding; sequence-specific double-stranded DNA binding; DNA-binding transcription factor activity; DNA-binding transcription factor activity, RNA polymerase II-specific; melatonin receptor activity; nuclear receptor activity; RNA polymerase II cis-regulatory region sequence-specific DNA binding; DNA binding; DNA-binding transcription activator activity, RNA polymerase II-specific; sequence-specific DNA binding; zinc ion binding
Biological process: amacrine cell differentiation; cellular response to retinoic acid; eye photoreceptor cell development; negative regulation of DNA-templated transcription; negative regulation of osteoblast differentiation; positive regulation of DNA-templated transcription; positive regulation of transcription by RNA polymerase II; regulation of circadian rhythm; regulation of DNA-templated transcription; regulation of transcription by RNA polymerase II; retina development in camera-type eye; retinal cone cell development; retinal rod cell development; G protein-coupled receptor signaling pathway; intracellular receptor signaling pathway; regulation of gene expression
Cellular component: nucleoplasm; chromatin; nucleus
Genetic constraint (gnomAD): Loss-of-function variants: 6 observed, 46 expected, observed/expected ratio (o/e) 0.13, 90% interval 0.07 to 0.26. The upper end of that interval is the gene's LOEUF score, 0.26, which puts it in group 1 of 6, group 1 being the genes least tolerant of losing a copy. Missense variants: 238 observed, 451.38 expected, observed/expected ratio (o/e) 0.53, 90% interval 0.47 to 0.59. Synonymous variants: 177 observed, 169.05 expected, observed/expected ratio (o/e) 1.05, 90% interval 0.93 to 1.19.
Gene-disease validity (ClinGen):
ClinGen rates the evidence that RORB causes each of these diseases.
complex neurodevelopmental disorder (autosomal dominant): Definitive. A disorder that involves more than one phenotype associated with the central nervous system, including but not limited to intellectual disability, autism, and seizures (epilepsy).
Homologues: Orthologues: macaque RORB (100% identical), chimpanzee RORB (99% identical), pig RORB (99% identical), rabbit RORB (99% identical), mouse Rorb (98% identical), rat Rorb (98% identical), guinea pig RORB (97% identical), dog RORB (97% identical), tropical clawed frog rorb (92% identical), zebrafish rorb (85% identical), Caenorhabditis elegans nhr-23 (34% identical), Caenorhabditis elegans sex-1 (23% identical), and 183 more. Paralogues in human: RORA (63% identical), RORC (51% identical), NR1D2 (30% identical), NR1D1 (29% identical), RARB (29% identical), RARG (28% identical), RARA (28% identical), THRB (24% identical), PPARG (23% identical), NR1H4 (23% identical), PPARA (23% identical), PPARD (22% identical), and 6 more.
Diseases named in the same sentence as RORB in open-access papers:
RORB is named in the same sentence as 78 diseases in open-access papers, as found by Europe PMC text mining. Sharing a sentence is not in itself a finding about the gene and the disease. The quoted sentences say what the papers report.
bipolar disorder (15 papers, 2009 to 2025). A disorder of the brain that causes unusual shifts in mood, energy, activity levels and the ability to carry out day-to-day tasks. "In humans, RORB is closely associated with bipolar disorder, cognitive function, and Alzheimer’s disease, indicating its pivotal role in neurocognitive processes." (PMID 39897619, 2024). "The RORB (Retinoic Acid Receptor-related orphan receptor β) gene plays a crucial role in neurodevelopment and is strongly associated with bipolar disorder, cognitive function, and Alzheimer’s disease." (PMID 39897619, 2024). "RORB gene variation was found associated with bipolar disorder in children, which in general have a more rapidly cycling clinical presentation than adults." (PMID 20856823, 2010). "The four intronic SNPs of RORB we found to be associated with bipolar disorder are all downstream of the first exon in both RORB1 and RORB2 transcripts." (PMID 19909500, 2009). "If certain sequence variants of RORB (these SNPs or others in linkage disequilibrium with them) do indeed represent susceptibility variants for bipolar disorder, it is possible they do so by altering the expression of one or both of the RORB isoforms." (PMID 19909500, 2009). "A role for RORβ variants in bipolar disorder has been suggested previously." (PMID 37300435, 2023). "Heterozygous deletion or loss of function of RORB in humans has been associated with epilepsy and genetic variants associated with Rorb are associated with bipolar disorder." (PMID 28112643, 2017). "Similarly, the RORB gene was also previously linked to psychiatric and neurological disorders, such as bipolar disorder and schizophrenia, in independent association studies." (PMID 28412756, 2017). "The RORB gene is a strong candidate for the neurological phenotype because RORB was deleted in all affected individuals, it is expressed in the cerebral cortex and thalamus, and genetic associations of RORB with bipolar disorder and verbal intelligence have been reported." (PMID 25950944, 2015). "Association studies of NR1D1, RORA, and RORB genes in bipolar disorder." (PMID 25789810, 2015). "In addition, we found no strong evidence for association between the age-at-onset of bipolar disorder with any RORA or RORB SNPs." (PMID 19909500, 2009). "The significant association of four RORB SNPs and three RORB haplotype blocks with bipolar disorder in the case-control sample indicates that this may indeed be the case." (PMID 19909500, 2009). "Here we report association studies for RORA and RORB in a pediatric bipolar disorder cohort." (PMID 19909500, 2009). "RORB was initially chosen for investigation due to its altered expression level in DBP knock-out mice (an animal model of bipolar disorder) and due to the potential role of circadian clock genes in bipolar disorder." (PMID 19909500, 2009). "We identified a potential association between bipolar disorder and the retinoid-related receptor RORB in a pediatric bipolar disorder cohort." (PMID 19909500, 2009). "It is therefore necessary to verify these association results in other independent samples and to continue to study the relationship between RORB, other clock genes, and bipolar disorder." (PMID 19909500, 2009). "In addition, recent studies from SNP tagging and genotyping manifest that there is a correlation between RORB and bipolar disorder." (PMID 40692708, 2025). "In addition, other clock genes were associated with these psychiatric disorders, such as Npas2 (winter depression, autism spectrum disorder and schizophrenia), RORA and RORB (bipolar disorder) or Tim, Dbp and Ck1ε (autism spectrum disorder)." (PMID 28468274, 2017). "Moreover, ARNTL, RORA, RORB and RXRG were associated with bipolar disorder in a meta-analysis integrating data from genome-wide association studies and human and animal model expression studies." (PMID 20195522, 2010).
bipolar disorder (continued). "Our findings suggest that clock genes in general and RORB in particular may be important candidates for further investigation in the search for the molecular basis of bipolar disorder." (PMID 19909500, 2009). "Despite these limitations, our results indicate that circadian clock genes in general and RORB in particular may be important candidates for genes involved in bipolar disorder." (PMID 19909500, 2009). "However, clinical reports with family histories demonstrating segregation of RORβ variants with either autism or bipolar disorders are lacking." (PMID 37300435, 2023). "A study reports that four intronic RORB SNPs showed positive associations with the pediatric bipolar phenotype and suggests that clock genes in general and RORB in particular may be important candidates for further investigation in the search for the molecular basis of bipolar disorder." (PMID 28468274, 2017). "Those unique to bipolar disorder were also enriched for circadian rhythm (PER3 and RORB)." (PMID 32398742, 2020). "Of note, both RORB and RORA have nominally suggestive signals in three recently reported genome-wide association studies for bipolar disorder that do not survive correction for multiple comparisons." (PMID 19909500, 2009).
breast cancer (15 papers, 2013 to 2025). A primary or metastatic malignant neoplasm involving the breast. "Studies have found that RORB is significantly associated with the risk of various cancers, including breast cancer, prostate cancer, lung cancer, etc.." (PMID 39981438, 2025). "In the context of neoplasms, RORB polymorphisms were associated with the development of breast cancer." (PMID 39744492, 2025). "For instance, the RORB SNP rs7867494 is associated with an increased incidence of breast cancer 17, and multiple RORB SNP variants are associated with the development of lung and prostate cancers." (PMID 39744492, 2025). "As age is the most common risk factor in breast cancer, it is interesting to note that the expression of RAR-related orphan receptor β (RORβ, also known as NR1F2) is greater in the postmenopausal breast compared to premenopausal tissue." (PMID 26300846, 2015). "Studies using the gene set analysis method confirmed an association with ARNTL, CLOCK, and RORA and additionally reported an association with RORB, RORC, CRY, and the overall pathway in relation to breast cancer risk." (PMID 40534841, 2025). "Additionally, a study demonstrated that RORB SNP rs3750420 variants are associated with the development of breast cancer 20, which could also explain the larger tumor size and tumor progression observed in buccal mucosa cancer in patients with this particular variant." (PMID 39744492, 2025). "The expression of RORB is also correlated with prognosis in breast cancer 25, with lower levels observed in the patients with endometrial cancer." (PMID 39744492, 2025). "Gene cluster B contained ERα and a group of NRs previously associated with ERα in breast cancer, including PGR, AR, RARα, LRH-1, PNR, as well as TRβ, RORβ, and RORγ." (PMID 26280373, 2015). "RORB has also been found to be a prognostic marker of breast cancer." (PMID 36311731, 2022). "Although its function is unclear, the ligands for RORβ may provide additional functional evidence of its roles in breast cancer cells." (PMID 26300846, 2015).
epilepsy (8 papers, 2015 to 2025). A brain disorder characterized by episodes of abnormally increased neuronal discharge resulting in transient episodes of sensory or motor neurological dysfunction, or psychic dysfunction. "In this study, we report a 5-year-old patient with epilepsy caused by a heterozygous variation in the RORB gene (c.94-1G>A)." (PMID 39897619, 2024). "To date, there have been limited reports of pathogenic variations in the RORB gene in epilepsy patients." (PMID 39897619, 2024). "Our findings offer valuable insights into the role of RORB in epilepsy pathogenesis, and the splice site variant identified in this study further expands the mutational spectrum of the RORB gene." (PMID 39897619, 2024). "Because of the reported involvement of RORβ variants in epilepsy, bipolar, and autism spectrum disorders, we chose to examine behavioral phenotypes related to cognition, sociability, and stereotypy in Rorbh5/h5 mice." (PMID 37300435, 2023). "We selected the brain because of the emerging relationship between RORβ variants and epilepsy, and we selected spinal cord because the profound gait phenotype observed in all strains is caused by dysfunction of spinal interneurons." (PMID 37300435, 2023). "A recent report identified novel inherited heterozygous RORB variants in fourteen individuals belonging to four families: eleven of them were affected by epilepsy, one had intellectual disability, and two were unaffected." (PMID 34768579, 2021). "Additionally, we provide a comprehensive summary of previously reported pathogenic or likely pathogenic variants in RORB, contributing to the growing body of evidence linking this gene to epilepsy." (PMID 39897619, 2024). "We chose assays that might reveal changes in social behavior, repetitive behaviors, and anxiety because of the associations between RORβ variants and neurodevelopmental conditions including epilepsy, bipolar, and autism spectrum disorders." (PMID 37300435, 2023). "In summary, it appears that RORB variants are mainly associated with different forms of epilepsy (including eyelid myoclonia with absence epilepsy, generalized epilepsy, and occipital epilepsy), often in comorbidity with neurodevelopmental disorders such as intellectual disability, ADHD, and ASD." (PMID 34768579, 2021). "In 2013, a report revealed that RORB has been deleted in all 13 cases with 9q21.13 microdeletion syndrome characterised by epilepsy, intellectual disability, speech delay, autism, and moderate facial deformities." (PMID 40692708, 2025). "There is strong evidence for the involvement of RORβ in epilepsy with multiple clinical reports describing familial and de novo variants, copy number variations, microdeletions, and balanced translocations in RORβ amongst epileptic patients." (PMID 37300435, 2023). "Microdeletions found only in GGE patients harboured a high proportion of genes previously associated with epilepsy and neuropsychiatric disorders (NRXN1, RBFOX1, PCDH7, KCNA2, EPM2A, RORB, PLCB1)." (PMID 25950944, 2015). "Similarly, a syndrome characterized by moderate facial dysmorphy, mental retardation, epilepsy, speech delay, and autistic behaviour in patients with a 9q21 deletion at the RORB locus identified RORβ as a strong candidate for this neurological disorder." (PMID 26878025, 2015). "These microdeletions affected 158 protein-coding RefSeq genes and exhibited an enrichment of genes previously associated with epilepsy (NRXN1, RBFOX1, PCDH7, KCNA2, EPM2A, RORB, PLCB1) and neuropsychiatric disorders (DPYD, CADM2, PARK2, GRM8, TSNARE1, TPH2, MACROD2)." (PMID 25950944, 2015). "RORB encodes RAR-related orphan receptor B (RORB), a receptor protein known to play an important role in bone metabolism, regulation of circadian rhythm, and other physiological processes, and mutation or abnormal expression of this gene is strongly associated with epilepsy." (PMID 38977948, 2024).
schizophrenia (8 papers, 2009 to 2024). A major psychotic disorder characterized by abnormalities in the perception or expression of reality. "GWAS studies revealed an association between a series of RORB genetic variants with schizophrenia, and bipolar I disorder and between RORβ expression in the temporal cortex and verbal intelligence." (PMID 26878025, 2015). "Variants in NDST4 were associated with ASD, variants in RORB were associated with childhood autism, and variants in SETBP1 were associated with schizophrenia." (PMID 34773992, 2021). "Tests for three genes obtained nominally significant p values: NDST4 in ASD, RORB in childhood autism, and SETBP1 in schizophrenia." (PMID 34773992, 2021). "For schizophrenia, we looked at the expression of OGFOD2 and RORB in the cerebellum." (PMID 38671846, 2024). "Finally, it is important to note that RORB, RORA, and DBP were identified by us recently as possible genes involved in schizophrenia using a pharmacogenomic mouse model and CFG approach." (PMID 19909500, 2009).
Anxiety (5 papers, 2012 to 2025). Intense feelings of nervousness, tension, or panic often arise in response to interpersonal stresses. "Rorb−/− mice exhibited damage in several neural reflexes, retinal degeneration, altered circadian activity, increased exploratory activity, less depressive-like behavior, reduced anxiety behavior, and ataxia, indicating RORB may be involved in sensory processing and emotional regulation." (PMID 40692708, 2025). "Nuclear receptor ROR-beta (RORB) influences circadian rhythms, which are critical for mood and anxiety regulation in this population." (PMID 39767679, 2024).
autism (5 papers, 2017 to 2025). Persistent deficits in social interaction and communication and interaction as well as a markedly restricted repertoire of activity and interest as well as repetitive patterns of behavior. "An in vitro study also demonstrated that RA can upregulate CD38 transcription levels; RA may regulate RORs (including RORA, RORB, RORR) through its retinoic acid receptors, which demonstrated the potential role of VA in autism biomarker." (PMID 28938872, 2017).
endometrial cancer (5 papers, 2013 to 2025). Primary or metastatic malignant neoplasm involving the endometrium (mucous membrane that lines the endometrial cavity). "The loss of RORB expression in endometrial cancer warrants further investigation." (PMID 23785665, 2013). "RORB expression was initially described to be restricted to the central nervous system, but it is also expressed in bone tissue, pancreatic and endometrial cancer, and uterine leiomyosarcoma." (PMID 38339014, 2024). "RORB, which had a high expression level in the endometrium in healthy pre- or post-menopausal women, was significantly down-regulated in endometrial cancer cells." (PMID 28137278, 2017). "RAR Related Orphan Receptor B (RORB) is mainly expressed in the central nervous system, retina, and pineal gland and is also differentially expressed in bone, pancreas, and endometrial carcinoma tissues." (PMID 36532015, 2022).